CCT3 (chaperonin containing TCP1 subunit 3)
Diseases named in the same sentence as CCT3 in open-access papers (continued):
Sharing a sentence is not in itself a finding about the gene and the disease.
cancer (33 papers, 2007 to 2025). A tumor composed of atypical neoplastic, often pleomorphic cells that invade other tissues. "The dysregulation of chaperonin-containing TCP-1 subunit 3 (CCT3) is implicated in several types of malignant tumors' development." (PMID 35399722, 2022). "As a subunit of TRiC family, CCT3 is a promising diagnostic biomarker for cancers and dysregulation of CCT3 contributes to cancer progression." (PMID 35773623, 2022). "Dysregulation of Chaperonin containing TCP-1 subunit 3 (CCT3) has been implicated in the development of several types of cancers." (PMID 29340068, 2017). "In addition, the KM curves showed that high CCT3 expression was associated with poor OS in 11 cancer types." (PMID 36313331, 2022). "The results showed the mutation frequency of CCT3 was rare in pan-cancer." (PMID 36313331, 2022). "The forest plot showed that CCT3 acted as a risk factor for OS in 12 cancer types." (PMID 36313331, 2022). "In addition, the colony-forming ability was clearly suppressed in shCCT3-1 and shCCT3-2 expressing cancer cells, indicating a lower duplicating potential associated with CCT3 knockdown (P<0.01, t-test)." (PMID 29340068, 2017). "In this article, we introduce the structure and function of CCT and CCT3, discussing the correlation between CCT3 and oncogenic factors, as well as the research progress of CCT3 in various cancers." (PMID 39928781, 2025). "In recent years, CCT3 has been reported to be abnormally expressed in various cancers, correlating with prognosis and therapeutic outcomes." (PMID 39928781, 2025). "Several CCT subunits, such as CCT2, CCT3, CCT4, CCT5, CCT6A, and CCT7, have been implicated in cancer progression." (PMID 40867231, 2025). "Although previous studies have confirmed abnormal expression of circRNA CCT3 and its involvement in cancer development, this study is the first to demonstrate the potential value of circRNA CCT3 in cancer diagnosis." (PMID 37833621, 2023). "Of the 8 components consisting of CCT/TRiC complex, CCT3 has been observed to overexpressed in various cancers including LUAD." (PMID 36918801, 2023). "Pan-cancer expression of CCT3 mRNA in a range of malignancies, displayed by the comparison between tumors and corresponding normal tissue counterparts, were investigated by using TCGA databases." (PMID 36918801, 2023). "As a chaperon protein, CCT3 was critical for cancer pathogenesis by regulating cell apoptosis, proliferation and energy metabolism." (PMID 36313331, 2022). "To take a closer step into the aberrant expression of CCT3 in pan-cancer, we analyzed CCT3 expression using a combined cohort of TCGA and GTEx in ACLBI." (PMID 36313331, 2022). "CCT3 also has an important role in the tumorigenesis of epithelial cells and the growth and survival of cancer cells." (PMID 36185198, 2022). "This study wanted to further explore CCT3’s roles through a comprehensive pan-cancer analysis workflow, contributing to revealing the similarity and difference among different tumors." (PMID 36313331, 2022). "The results showed that CCT3 expression was up-regulated in 20 cancer types and down-regulated in three cancer types." (PMID 36313331, 2022). "The results showed that the transcript of CCT3 was increased in cancer tissues compared with normal tissues." (PMID 35773623, 2022). "CCT3 is overexpressed in various cancers, such as liver cancer, cervical cancer, papillary thyroid carcinoma and gastric cancer." (PMID 35409343, 2022). "This study aimed to further explore the characteristics of CCT3 from a pan-cancer perspective and reveal the driving forces for CCT3." (PMID 36313331, 2022). "Then we calculated the ranking of CCT3 expression among the differentially expressed genes in the 8 high-expressed cancer types." (PMID 36313331, 2022). "To further explore the functions of CCT3 in cancers, we obtained the CCT3-related genes through the online analysis tools String and GENEMANIA." (PMID 36313331, 2022).
cancer (continued). "Collectively, CCT3 plays a key role in cancer cell division, proliferation, metabolism and drug resistance." (PMID 36313331, 2022). "Intriguingly, we noticed that higher transcriptional levels of CCT3 were correlated with more advanced cancer stages." (PMID 35409343, 2022). "In this study, a systematic pan-cancer analysis of CCT3 was performed by bioinformatics and experiments." (PMID 36313331, 2022). "Although CCT3 has been widely investigated in diverse cancers, its involvement in drug resistance remains elusive." (PMID 34612768, 2021). "Significant upregulation of TCP1, CCT2/3/5/6A/8 levels have been found in a variety of cancers, with CCT3/6A/8 the best studied in HCC, while there are few studies on CCT4/5/7." (PMID 34676169, 2021). "The mRNA profiles of CCT3 were increased in different types of cancers versus the corresponding normal tissue." (PMID 34505628, 2021). "With a dramatic decrease of CCT3 expression, the proliferation of the cancer cells in culture was significantly inhibited as shown by a nearly flat growth curve after lentiviral infection." (PMID 29340068, 2017). "Further studies on the mechanisms of CCT3 function is mandated to develop novel cancer treatment targeting CCT3." (PMID 29340068, 2017). "The effects of CCT3 knockdown on cancer cell proliferation, apoptosis and in vivo growth were examined." (PMID 29340068, 2017). "When CCT3 is knocked down, the Wnt/β-catenin signaling pathway, along with downstream target genes such as cyclin D1 and c-myc, is suppressed, ultimately affecting cancer cell proliferation and tumorigenesis." (PMID 39928781, 2025). "CCT3 deregulation disrupts proteostasis, contributing to cancer development and progression." (PMID 41153715, 2025). "It is known that CCT3 plays a key role in cancer cell division, proliferation, metabolism, and drug resistance; furthermore, as a part of the TRiC chaperonin complex, it is involved in telomere elongation maintenance by assisting the proper folding of the telomerase-associated protein TCAB1." (PMID 40647238, 2025). "The dysregulation of CCT3 disrupts proteostasis, promoting cancer development." (PMID 41153715, 2025). "Notably, two previous studies have also shown that circRNA CCT3 promotes distal metastasis of cancer cells and EMT." (PMID 37833621, 2023). "In a comparison of the control with cancer group (grade 4), the 5-marker panel (CCT3, PCMT1, TKT, TOMM34, UBA1) showed better sensitivity (0.90 and 0.90), specificity (0.93 and 1.00), error rate (8 and 4%), and AUC value (0.94 and 0.96) than the best single marker (TOMM34)." (PMID 37875819, 2023). "Western blot results showed that CCT3 was upregulated at protein level in cancer tissues." (PMID 35773623, 2022). "As a subunit of TRiC family, CCT3 plays a pivotal role in cancer progression." (PMID 35773623, 2022). "Then we calculated the relevance between CCT3 expression and the prognosis in 33 cancer types." (PMID 36313331, 2022). "Besides, we found a close correlation between CCT3 expression and pathological stages of multiple cancer types, including KICH, KIRP, LIHC, LUAD, LUSC and STAD." (PMID 36313331, 2022). "In the 33 cancer types, we found abnormal high expression of CCT3 in 27 of these cancer types." (PMID 36313331, 2022). "Our study showed a widespread high expression of CCT3 in pan-cancer, especially in 8 cancer types, suggesting that CCT3 may function as an oncogene in tumors." (PMID 36313331, 2022). "Moreover, based on the TCGA datasets, we analyzed the CCT3 differential expression levels between carcinomas and adjacent tissues." (PMID 36313331, 2022). "In addition, knockdown of CCT3 with a special siRNA in HNSCC cell lines leaded to the growth suppression of cancer cells, which is consistent with studies in other cancers." (PMID 34505628, 2021). "An important subunit of CCT, CCT3, has been extensively studied in various cancer contexts." (PMID 34612768, 2021).
cancer (continued). "Meanwhile, abnormal high expression of CCT3 was related with DFI and PFI in six cancers and 9cancers, respectively." (PMID 36313331, 2022). "However, the concrete roles of CCT3 in human cancers still remain unclear." (PMID 35399722, 2022). "All eight CCT subunits showed significant (p< 0.0001) upregulation in RNAseq expression in cancer compared to normal tissue, with the strongest upregulation seen in CCT2 and CCT3, S1A Fig." (PMID 35749519, 2022). "CCT3 RNA stoichiometry data further suggested an enrichment of a chaperonin-independent function in HCC when compared with healthy tissue and 14 other cancer types." (PMID 35022268, 2022). "Some of the genes were reported as cancer-related genes, such as CCT2, CCT3, CCT4, CCT6A, CCT7, CCT8." (PMID 33897772, 2021). "CCT3 is a subunit of chaperonin-containing TCP-1 (CCT), which folds many proteins involved in cancer development and plays an important role in many cancers." (PMID 32518527, 2020). "CCT3 may regulate IGF-1 signaling, actin cytoskeletal signaling, and PTEN signaling pathways, which are known to function in epithelial tumorigenesis and cancer cell growth and play an important role in survival." (PMID 36185198, 2022). "In spite of the mounting evidence indicating that CCT3 is critical for tumorigenesis and cancer progression, the potential role of CCT3 in regulating drug resistance has not been investigated." (PMID 34612768, 2021). "Chaperonin containing TCP1 subunit 3 (CCT3) has been extensively investigated in various cancers, but not in the context of drug resistance." (PMID 34612768, 2021). "CCT3 is an important subunit of CCT and is widely studied in different cancers." (PMID 32518527, 2020). "We also identified six predicted SQLE, CCT3, IDI1, GBA, MTR, and NCSTN cancer drug target genes." (PMID 31216110, 2019). "Moreover, we found a significant negative correlation of CCT3 expression with a variety of immune cells in various carcinomas." (PMID 36313331, 2022). "However, the roles of CCT3 in pan-cancer are not compared, especially from the immune aspect." (PMID 36313331, 2022).
infection (3 papers, 2017 to 2025). The state of being infected such as from the introduction of a foreign agent such as serum, vaccine, antigenic substance or organism. "After infection, CCT3 expression decreased by 88.4% and 75.4% in A375 and MUM-2C cells, respectively, compared with that in the shCtrl group." (PMID 35399722, 2022). "After five days of infection, the number of CCT3-shRNA-infected A375 or MUM-2C cells was significantly reduced compared with that of scr-shRNA-infected cells (P < 0.001)." (PMID 35399722, 2022). "After infection, the expression of CCT3 gene decreased by 94.6% and 95.7% in BGC-823 and MGC-803 cells compared with the shCtrl group, respectively." (PMID 29340068, 2017). "In the context of human papillomavirus (HPV) infections, CCT3 and CCT2 knockdown resulted in reduced infection levels of 40% and 25%, respectively." (PMID 39928781, 2025).
gastrointestinal tumor (1 paper, 2022). "More importantly, enhancer inhibitors (JQ1 and I-BET-762) or BRD4 knockdown attenuated CCT3 expression in gastrointestinal tumor cells." (PMID 36313331, 2022).
CCT3 also shares sentences with these, for which no sentence is quoted: colorectal cancer (3 papers); myotonic dystrophy type 2 (3); myotonic dystrophy type 1 (2); thyroid cancer (2); acute myeloid leukemia (1); blastoma (1); ciliopathies (1); colonic carcinoma (1); esophageal squamous cell carcinoma (1); floor of the mouth carcinoma (1); genetic disease (1); hepatitis B (1); Intellectual disability (1); liver diseases (1); lymph-node metastasis (1); medulloblastoma (1); Myotonia (1); myotonic dystrophy (1); neurological disorders (1); oral cavity carcinoma (1); oropharyngeal carcinoma (1); rectal cancer (1); rectal tumors (1); renal fibrosis (1); Squamous Cell Carcinoma of the Cervix (1); tongue cancer (1); tonsillar carcinoma (1).